EBNA1BP2 (EBNA1 binding protein 2)
Description:
Required for the processing of the 27S pre-rRNA.
Synonyms: EBP2; NOBP; P40
Tractability: Small molecule: a structure with a bound ligand is known. PROTAC: UniProt records ubiquitination sites on it; ubiquitination databases record sites on it; its protein half-life has been measured.
Gene: Protein-coding gene on chromosome 1 (43,164,175 to 43,270,936, reverse strand). Ensembl gene ENSG00000117395.
Subcellular location: Nucleus, nucleolus
Subcellular location (Human Protein Atlas): Nucleoli; Nucleoli rim; Mitotic chromosome
Pathways (Reactome):
Metabolism of RNA: Major pathway of rRNA processing in the nucleolus and cytosol
Gene Ontology:
Molecular function: protein binding; RNA binding
Biological process: rRNA processing
Cellular component: chromosome; nucleolus; nuclear periphery; preribosome, large subunit precursor
Genetic constraint (gnomAD): Loss-of-function variants: 35 observed, 46.11 expected, observed/expected ratio (o/e) 0.76, 90% interval 0.58 to 1.01. The upper end of that interval is the gene's LOEUF score, 1.01, which puts it in group 4 of 6, group 1 being the genes least tolerant of losing a copy. Missense variants: 321 observed, 380.21 expected, observed/expected ratio (o/e) 0.84, 90% interval 0.77 to 0.93. Synonymous variants: 122 observed, 142.74 expected, observed/expected ratio (o/e) 0.85, 90% interval 0.74 to 0.99.
Homologues: Orthologues: chimpanzee EBNA1BP2 (100% identical), macaque EBNA1BP2 (98% identical), guinea pig EBNA1BP2 (91% identical), pig EBNA1BP2 (88% identical), rabbit EBNA1BP2 (87% identical), mouse Ebna1bp2 (85% identical), rat Ebna1bp2 (84% identical), tropical clawed frog ebna1bp2 (67% identical), dog EBNA1BP2 (57% identical), zebrafish ebna1bp2 (56% identical), Caenorhabditis elegans C18A3.3 (36% identical), Drosophila melanogaster CG1542 (35% identical).
Diseases named in the same sentence as EBNA1BP2 in open-access papers:
EBNA1BP2 is named in the same sentence as 14 diseases in open-access papers, as found by Europe PMC text mining. Sharing a sentence is not in itself a finding about the gene and the disease. The quoted sentences say what the papers report.
COVID-19 (1 paper, 2022). A disease caused by infection with severe acute respiratory syndrome coronavirus 2. "EBNA1BP2 has been confirmed to be one of the hub genes in COVID-19 susceptibility and was related to the levels of infiltrating immune cells, including CD4+ activated memory T cells, follicular helper T cells and plasma cells." (PMID 36457997, 2022).
lung carcinoma (1 paper, 2020). "Both protein and mRNA levels of EBNA1BP2 were reported to be upregulated in lung cancer samples." (PMID 32953881, 2020).
melanoma (1 paper, 2018). A malignant, usually aggressive tumor composed of atypical, neoplastic melanocytes. "Nop56 and Ebna1bp2 also interacted with Csde1 in melanoma cells." (PMID 29422612, 2018).
Sepsis (1 paper, 2024). Sepsis is defined as life-threatening organ dysfunction caused by a dysregulated host response to infection. "Thus, it can be currently considered that EBNA1BP2 and PES1 may be involved in the pathological process of sepsis and SIM by regulating the number and function of B lymphocytes." (PMID 39438952, 2024).
cancer (2 papers, 2020 to 2021). A tumor composed of atypical neoplastic, often pleomorphic cells that invade other tissues. "Also, the roles of GINS2 and EBNA1BP2 in PCa could be reflected by their associations with other cancers." (PMID 32953881, 2020). "EBNA1BP2 may promote cancer cell proliferation by blocking the degradation of oncogene c-Myc." (PMID 32953881, 2020).
EBNA1BP2 also shares sentences with these, for which no sentence is quoted: malaria (3 papers); infection (2); colorectal cancer (1); diabetic retinopathy (1); heart failure (1); hepatocellular carcinoma (1); Hyperglycemia (1); retinopathy of prematurity (1); tumor (1).